MAGEB1 (MAGE family member B1)
Synonyms: CT3.1; DAM10; MAGEL1; MAGE-Xp; MGC9322
Tractability: PROTAC: ubiquitination databases record sites on it.
Gene: Protein-coding gene on chromosome X (30,243,715 to 30,252,041, forward strand). Ensembl gene ENSG00000214107.
Gene Ontology:
Biological process: negative regulation of transcription by RNA polymerase II
Cellular component: nucleus; cytoplasm
Homologues: Orthologues: chimpanzee MAGEB1 (98% identical), macaque MAGEB1 (91% identical), zebrafish ndnl2 (22% identical), Drosophila melanogaster MAGE (20% identical). Paralogues in human: MAGEB4 (67% identical), MAGEB2 (60% identical), MAGEB17 (53% identical), MAGEB18 (52% identical), MAGEB3 (50% identical), MAGEB10 (50% identical), MAGEB6B (48% identical), MAGEB6 (48% identical), MAGEA10 (45% identical), MAGEB16 (43% identical), MAGEA4 (41% identical), MAGEA11 (40% identical), and 25 more.
Diseases named in the same sentence as MAGEB1 in open-access papers:
MAGEB1 is named in the same sentence as 11 diseases in open-access papers, as found by Europe PMC text mining. Sharing a sentence is not in itself a finding about the gene and the disease. The quoted sentences say what the papers report.
hypoglycaemia (1 paper, 2014). "Our array data indicated that two MAGE genes were demethylated by hypoxia (MAGEA11) and hypoglycaemia (MAGEB1), though no induction in expression was observed." (PMID 25079072, 2014).
systemic lupus erythematosus (1 paper, 2005). An autoimmune multi-organ disease typically associated with vasculopathy and autoantibody production. "The exceptions to this are humoral immune responses to MAGEB1/CT3.1 in systemic lupus erythematosus patients and to SPA17/CT22 in vasectomised men." (PMID 15715909, 2005).
teratocarcinoma (1 paper, 2019). A germ cell tumor characterized by the presence of an embryonal carcinoma component and a teratoma component. "Two gene clusters including Mage-a4 and Mage-a8, Mageb1, Mage-d1, Mage-d2, Mage-e1, Mage-l2 were identified as functional antagonists with opposing roles in the regulation of proliferation and differentiation of mouse pluripotent stem and teratocarcinoma cells." (PMID 31143371, 2019).
tumor (4 papers, 2017 to 2025). "LOC100363492 (Ly6k), MGC114427 (Magea9), and Mageb1 are known as tumor antigens and were all expressed at a lower level in MLL- than in AT1-tumors, especially Ly6k." (PMID 28472073, 2017). "The positive prognostic value of MAGEB1 could be attributed to its ability to elicit a strong immune response, thereby aiding the body in identifying and combating tumor cells more effectively." (PMID 39120328, 2024). "A high level of MAGEB1 expression could indicate an active immune response against the tumor, contributing to a more favorable prognosis." (PMID 39120328, 2024). "Furthermore, the expression of MAGEB1 in tumors may serve as a biomarker for immune activity within the tumor microenvironment." (PMID 39120328, 2024).
cancer (2 papers, 2024 to 2025). A tumor composed of atypical neoplastic, often pleomorphic cells that invade other tissues. "The MAGE family, particularly the B subset to which MAGEB1 belongs, has been studied for its expression in various malignancies and its potential as a target for cancer immunotherapy." (PMID 39120328, 2024).
MAGEB1 also shares sentences with these, for which no sentence is quoted: breast carcinoma (1 paper); carcinosarcoma (1); Colon Cancer (1); esophageal carcinoma (1); gastric carcinoma (1); melanoma (1).